GGH (gamma-glutamyl hydrolase)
Description:
Hydrolyzes the polyglutamate sidechains of pteroylpolyglutamates. Progressively removes gamma-glutamyl residues from pteroylpoly-gamma-glutamate to yield pteroyl-alpha-glutamate (folic acid) and free glutamate. May play an important role in the bioavailability of dietary pteroylpolyglutamates and in the metabolism of pteroylpolyglutamates and antifolates.
Synonyms: GATD10; GH
Tractability: Small molecule: it belongs to a druggable protein family. Antibody: UniProt places it where antibodies can reach, with high confidence; its Gene Ontology location is reachable by antibodies, with high confidence; UniProt predicts a signal peptide or a membrane-spanning region. PROTAC: ubiquitination databases record sites on it; its protein half-life has been measured; a small molecule that binds it is known.
Target class: Protease; Cysteine protease C26 family; Cysteine protease; Enzyme; Cysteine protease PCC clan
Safety:
Unwanted effects reported when the protein is acted on. In parentheses: how it was acted on, where the effect was seen, and who reports it.
accumulation of active methotrexate metabolites (source: ClinPGx)
bone marrow toxicity (source: ClinPGx)
drug toxicity (source: ClinPGx)
thrombocytopenia (source: ClinPGx)
Gene: Protein-coding gene on chromosome 8 (63,014,881 to 63,039,407, reverse strand). Ensembl gene ENSG00000137563.
Subcellular location: Secreted, extracellular space; Lysosome; Melanosome
Subcellular location (Human Protein Atlas): Vesicles; Endoplasmic reticulum
Pathways (Reactome):
Immune System: Neutrophil degranulation
Gene Ontology:
Molecular function: gamma-glutamyl-peptidase activity; protein binding; exopeptidase activity; omega peptidase activity; hydrolase activity
Cellular component: endoplasmic reticulum; extracellular exosome; extracellular region; lysosome; melanosome; nucleus; azurophil granule lumen; specific granule lumen; tertiary granule lumen
Genetic constraint (gnomAD): Loss-of-function variants: 4 observed, 6 expected, observed/expected ratio (o/e) 0.67, 90% interval 0.33 to 1.49. That is too few expected variants to judge how well the gene tolerates losing a copy. Missense variants: 105 observed, 77.69 expected, observed/expected ratio (o/e) 1.35, 90% interval 1.15 to 1.59. Synonymous variants: 47 observed, 33.2 expected, observed/expected ratio (o/e) 1.42, 90% interval 1.12 to 1.79.
Homologues: Orthologues: chimpanzee GGH (99% identical), macaque GGH (96% identical), dog GGH (76% identical), pig GGH (76% identical), rabbit GGH (76% identical), guinea pig GGH (72% identical), mouse Ggh (70% identical), rat Ggh (68% identical), tropical clawed frog ggh (58% identical), zebrafish ggh (54% identical), Drosophila melanogaster l(3)72Dp (36% identical), Drosophila melanogaster l(3)72Dr (28% identical).
Diseases named in the same sentence as GGH in open-access papers:
GGH is named in the same sentence as 73 diseases in open-access papers, as found by Europe PMC text mining. Sharing a sentence is not in itself a finding about the gene and the disease. The quoted sentences say what the papers report.
breast carcinoma (6 papers, 2013 to 2025). "Of note, hormone-dependent regulation of GGH is also supported by a recent study showing strong associations of GGH and estrogen/progesterone receptor levels in breast cancer." (PMID 28146062, 2017). "Similarly, high GGH expression was significantly associated with histological tumor grade in breast cancer (BRE III, p < 0.001)." (PMID 35082830, 2021). "Furthermore, the elevated levels of GGH was found to be correlated with shorter RFS with more than 35 fold increased risk, suggesting that GGH expression may predict the recurrence behavior of breast cancer." (PMID 23374458, 2013). "High levels of GGH mRNA expression are significantly correlated with more advanced histological type, vascular invasion, and poor survival rate compared to low GGH expression levels in cervical cancer, gallbladder cancer, and breast cancer." (PMID 35082830, 2021). "It was reported that GGH expression was significantly associated with a high histological tumor grade (BRE grade III, P < 0.001), as well as ER/PR receptors in patients with breast cancer." (PMID 31754833, 2020). "Our findings suggest that GGH serve as a potential biomarker of unfavorable clinical outcomes over short-term follow-up in breast cancer." (PMID 23374458, 2013). "However, GGH overexpression was demonstrated to be insufficient to produce resistance to the drug in a human fibrosarcoma (HT-1080) and a human breast carcinoma (MCF-7) cell line." (PMID 24944581, 2014). "In addition, GGH accumulation may reflect a functional correlation with FAAH expression, which could play a role in the progression of breast carcinoma." (PMID 23374458, 2013). "Paired breast cancer tissues and adjacent non-cancerous tissues have been found to express GGH differentially, with the cancer tissues displaying significantly higher expression of GGH protein." (PMID 23374458, 2013).
colorectal cancer (6 papers, 2008 to 2025). A primary or metastatic malignant neoplasm that affects the colon or rectum. "Tumor-associated upregulation of GGH has indeed been reported also for various other human cancers, including, for example, urothelial carcinoma of the bladder, breast, lung, or colorectal cancer." (PMID 28146062, 2017). "Moreover, we have reported that a reduction in GGH gene expression was associated with the response to UFT/LV chemotherapy in patients with colorectal cancer." (PMID 28417167, 2017). "The present study measured the mRNA expression levels of TS, DPD, TP, FPGS, GGH and DHFR, enzymes that are important in the chemotherapy of colorectal cancer with 5-FU-based agents, and examined the associations between such levels and DFS." (PMID 25364408, 2014). "As the folate metabolism is complex, it was suggested that gamma-glutamylhydrolase (GGH) expression may help to predict leucovorin efficacy in colorectal cancer patients." (PMID 40465055, 2025). "The genes BCAT1, GGH and SERPINB9 have been correlated to clinical outcome in other types of cancer, such as colorectal cancer, neuroendocrine cancer, large cell lymphoma and melanoma." (PMID 18778486, 2008).
gastric cancer (4 papers, 2017 to 2021). A primary or metastatic malignant neoplasm involving the stomach. "In gastric cancer patients as well, high GGH mRNA expression was significantly associated with histological type and vascular invasion." (PMID 35082830, 2021). "In contrast, the 5-years OS rate of gastric cancer patients with high GGH mRNA expression level was significantly lower than that of patients with low GGH expression." (PMID 35082830, 2021). "Our results are consistent with these findings, as the expression levels of GGH mRNA were found to be significantly higher in the gastric cancer tissue than in the paired adjacent normal mucosa." (PMID 31754833, 2020). "In patients with stage II/III gastric cancer, TOP2A, GGH, and PECAM1 levels in primary tumors are linked to high risk of hematogenous, lymph node, and peritoneal recurrence, respectively." (PMID 28915696, 2017). "GGH expression was significantly higher in gastric cancer tissue than in adjacent normal mucosa." (PMID 31754833, 2020). "Recently, it was reported that high GGH expression is a risk factor of lymph node recurrence after surgery in patients with stage II/III gastric cancer, using clinical specimens of ACTS-GC." (PMID 31754833, 2020). "The relationship between the expression levels of GGH and FPGS mRNA in cancer tissue and long-term outcomes in patients with stage II/III gastric cancer was then assessed." (PMID 31754833, 2020). "Here, the clinical significance of GGH and FPGS expression was investigated in Stage II/III gastric cancer patients undergoing postoperative adjuvant chemotherapy with S-1." (PMID 31754833, 2020). "Next, the relationship between the expression levels of GGH and FPGS mRNA and the clinicopathological features in patients with stage II/III gastric cancer were examined." (PMID 31754833, 2020). "GGH and FPGS mRNA expression was measured by qPCR to evaluate their clinicopathological significance in gastric cancer patients after curative resection." (PMID 31754833, 2020). "First, the expression levels of GGH and FPGS mRNA in gastric cancer tissue and adjacent normal mucosa were compared." (PMID 31754833, 2020). "Many reports have shown that GGH is involved in the ERG-negative prostate cancer and gastric cancer development by multiple methods." (PMID 31815134, 2019). "PECAM1 mRNA levels were higher in diffuse-type than in intestinal-type gastric cancer, whereas the opposite was true for TOP2A and GGH expression (P < 0.0001)." (PMID 28915696, 2017). "The elucidation of the mechanism whereby high levels of GGH expression and low levels of FPGS expression could be used as prognostic biomarkers in patients with locally advanced gastric cancer for which the administration of postoperative adjuvant chemotherapy with S-1 is not currently sufficient." (PMID 31754833, 2020). "In conclusion, high levels of GGH mRNA expression and low levels of FPGS mRNA expression in cancer tissue may be useful predictive biomarkers for the survival of patients with stage II/III gastric cancer undergoing postoperative adjuvant chemotherapy with S-1 after radical resection." (PMID 31754833, 2020). "Elevated GGH expression was found in breast, ERG-negative prostate, gallbladder, and gastric cancers compared to matched noncancerous tissues." (PMID 35082830, 2021). "In this study, we measured the levels of GGH and FPGS mRNA expression in cancer tissues and adjacent normal mucosa in patients with stage II/III gastric cancer." (PMID 31754833, 2020).
invasive breast carcinoma (4 papers, 2013 to 2024). A carcinoma that infiltrates the breast parenchyma. "Additionally, a recent study has shown that the expression level of GGH is associated with poor prognosis and unfavorable clinical outcomes in invasive breast cancer." (PMID 38166892, 2024). "Previous studies have confirmed that GGH is highly expressed in invasive breast cancer and ERG-negative prostate cancer in comparison with adjacent non-cancerous tissues and high GGH levels are related to poor prognosis and unfavorable clinical outcomes." (PMID 31105744, 2019).
prostate carcinoma (4 papers, 2017 to 2021). A carcinoma that arises from epithelial cells of the prostate gland. "GGH overexpression was weakly linked to adverse features of prostate cancer in our study, including advanced tumor stage, high Gleason grade, and early biochemical recurrence." (PMID 28146062, 2017). "To generate hypotheses on the molecular mechanisms associated with GGH upregulation during prostate cancer development and progression we exploited the molecular database attached to our TMA." (PMID 28146062, 2017). "For instance, the 10-years recurrence-free survival rate of ERG-negative prostate cancer patients with high GGH expression levels was significantly higher than that of patients with low GGH expression levels." (PMID 35082830, 2021). "GGH expression levels were only marginally related to prostate cancer clinical characteristics if all cancers were jointly analyzed." (PMID 28146062, 2017). "Our immunhistochemical analysis showed detectable GGH staining in 88.3% of 10,562 interpretable prostate cancers." (PMID 28146062, 2017). "Given the increasing evidence for a role of GGH in cancer, we became interested in its role in prostate cancer." (PMID 28146062, 2017). "That GGH expression increased only slightly with tumor stage and Gleason grade supports a role of GGH upregulation already in early stages of prostate cancer." (PMID 28146062, 2017). "GGH staining was detectable in 9322 of our 10,562 (88.3%) interpretable prostate cancers, and was considered as “low intensity” in 49.6% and as “high intensity” in 38.6% of cancers." (PMID 28146062, 2017). "Finding GGH expression in about 90% of our prostate cancers may provide an explanation for the poor response against 5-FU-based therapies." (PMID 28146062, 2017). "That about 40% of our cancers showed stronger GGH staining than normal prostate glands suggests that GGH may become upregulated during prostate cancer development and/or progression." (PMID 28146062, 2017). "It is, thus, tempting to speculate that GGH upregulation may occur in early prostate cancer progression." (PMID 28146062, 2017). "Given its statistical independence of established prognostic features, it cannot be excluded, that GGH expression measurement may aid in decision-making in ERG-negative prostate cancers if combined with other markers." (PMID 28146062, 2017). "The relationship between GGH expression, androgen receptor (AR) expression, and ERG activation was analyzed because of the central role of AR for prostate cancer, and because ERG activation is the most frequent molecular alteration in this tumors." (PMID 28146062, 2017). "We, therefore, studied the expression of GGH by immunohistochemistry on a large tissue microarray (TMA) including more than 12,400 prostate cancers." (PMID 28146062, 2017). "Studies on GGH expression and its potential impact on prostate cancer biology are currently lacking." (PMID 28146062, 2017). "Employing GGH immunohistochemistry on a tissue microarray with 12,427 prostate cancers, we found that GGH expression was negative to low in normal prostate epithelium, whereas 88.3% of our 10,562 interpretable cancers showed GGH expression." (PMID 28146062, 2017). "Others have so far not examined GGH in prostate cancer but the high fraction of GGH-positive tissue samples is well in line with the ubiquitous expression of GGH described in human tissues." (PMID 28146062, 2017).
acute leukemia (3 papers, 2013 to 2017). A clonal (malignant) hematopoietic disorder with an acute onset, affecting the bone marrow and the peripheral blood. "Either methylation of CpG1 or hypermethylation of CpG2 in GGH promoter region can significantly reduce GGH mRNA expression in pediatric patients with acute leukemia, which can improve the response to treatment." (PMID 28278270, 2017). "In patients with acute leukemia, it was reported that the activity of GGH and FPGS in blast cells is a good predictor of the relative levels of MTXPG3-5, with lower FPGS and/or higher GGH activity leading to reduced MTX polyglutamation." (PMID 27752107, 2016). "Furthermore, GGH expression was found to act as a prognostic biomarker for acute leukemia in response to methotrexate therapy." (PMID 23374458, 2013).
colon cancer (3 papers, 2019 to 2025). "The overexpression of GGH in colon cancer-derived cell lines (SW48 and SW480) inhibited PKM, GLUT1, and LDHA expression and decreased the extracellular lactate content and intracellular ATP level." (PMID 36569910, 2022). "A quantitative analysis indicated that GGH was more highly expressed in colon cancer tissues than in normal tissues (p < 0.001) and paired para-cancerous tissues (p < 0.001)." (PMID 36569910, 2022). "Our results provide insight into the connection between metabolism and the tumor microenvironment in colon cancer and provides preliminary evidence for the role of GGH, providing a basis for subsequent studies." (PMID 36569910, 2022). "GGH was upregulated in colon cancer; its high expression was correlated with CD4+ T cell infiltration and longer overall survival and it was identified as a favorable independent prognostic factor." (PMID 36569910, 2022). "Lower expression of GGH enhances sensitivity of cancer cells to pemetrexed, 5-fluorouracil, methotrexate, and gemcitabine in colon cancer, advanced pancreatic cancer, and non-small cell lung cancer." (PMID 31105744, 2019). "Furthermore, GGH expression was positively related to the infiltration of CD4+ T cells in colon cancer in clinical samples." (PMID 36569910, 2022). "The expression of GGH was lower in both tumor and mucosa of right-sided and MSI-H colon cancers compared to left-sided and MSS/MSI-L cases." (PMID 39998667, 2025). "The basal expression levels of GGH in a colonic epithelial cell line (NCM460) and colon cancer-derived cell lines (LOVO, CACO-2, SW48, and SW480) were detected using RT-qPCR and western blotting." (PMID 36569910, 2022). "GGH, CACNG4, MME, SLC30A2, CKMT2, SYN3, and SLC22A31 were identified as differentially expressed both in glycolytic-cholesterogenic subgroups as well as between colon cancers and healthy samples, and were involved in glycolysis‒cholesterol synthesis." (PMID 36569910, 2022).
COVID-19 (3 papers, 2022 to 2025). A disease caused by infection with severe acute respiratory syndrome coronavirus 2. "Clusters A to C contain proteins with lower levels in COVID-19 convalescents, e.g. proteins functioning in cell adhesion and platelet degranulation (e.g. fibrinogen A (FGA), VWF), and innate immunity/the complement system (e.g. C1R, C1S, C1QA, C1QC, and GGH)." (PMID 38396092, 2024). "Interestingly, blood GGH levelsare upregulated in nonsevere COVID-19 compared to healthy controlsand showed a significant tendency to increase as the disease progresses(Bi_1, Lee_1, and Shen_1 data sets)." (PMID 39803891, 2025).
folate deficiency (3 papers, 2017 to 2021). A nutritional condition produced by a deficiency of FOLIC ACID in the diet. "GGH is involved in glutamate removal from folate signals in IPA analysis, and overexpression of GGH can lead to more efflux of folate, which might result in folate deficiency." (PMID 34447787, 2021).
glioma (3 papers, 2020 to 2025). A benign or malignant brain and spinal cord tumor that arises from glial cells (astrocytes, oligodendrocytes, ependymal cells). "Because only glioma-related proteins were used for targeted quantification, only the GGH and NCAM1 proteins showed differential abundance between moyamoya disease patients and healthy controls." (PMID 32922940, 2020).
leukemia (3 papers, 2008 to 2017). A malignant (clonal) hematologic disorder, involving hematopoietic stem cells and characterized by the presence of primitive or atypical myeloid or lymphoid cells in the bone marrow and the blood. "A recent study in leukaemia found that hypermethylation of the GGH promoter was associated with silencing of GGH gene expression." (PMID 18414409, 2008). "In one case, the abundance of GGH was similar between the paired cells; and in two cases, the abundances were higher in leukemia cells than in the paired normal leukocytes (by factors of 3.8 and 7.2)." (PMID 28278270, 2017). "In leukemia cells, methylation in CpG1 down-regulated GGH expression effectively and methylation in both CpG1 and CpG2 significantly reduced GGH expression." (PMID 28278270, 2017). "GGH mRNA abundances were similar between the paired cells in samples obtained from the one patient whose leukemia cells contain only methylated in CpG1 alone." (PMID 28278270, 2017). "In sumarry, our findings show that GGH mRNA abundance in human leukemia cells could be altered by methylation of CpG1 and hypermethylation of CpG2." (PMID 28278270, 2017). "Our results indicate that either methylation of CpG1 or hypermethylation (greater than 10% methylation) of CpG2 could significantly reduce GGH mRNA expression in leukemia cells from ALL and AML patients." (PMID 28278270, 2017). "The GGH gene is involved in reversing polyglutamation by removing glutamate moieties, and a specific functional SNP (452C > T) in the human GGH gene is associated with lower catalytic activity and greater accumulation of long-chain MTX-PGs in leukemia cells of patients treated with high-dose MTX." (PMID 27980801, 2016). "Further analysis shows that leukemia cells from the ALL patients whose CpG2 exhibits a methylation level greater than Grade I (which was defined as hypermethylation in this study) correlates with significantly reduced GGH mRNA expression (1.3533±1.7306, t = 3.250, P = 0.006)." (PMID 28278270, 2017). "In samples obtained from 7 out of 10 patients whose leukemia cells did not contain methylated CpG1, GGH mRNA was more abundant (by a factor of 1.7–10.8) in these leukemia cells than in the paired normal leukocytes." (PMID 28278270, 2017).